RNU6-216P (RNA, U6 small nuclear 216, pseudogene)
Gene: Small nuclear RNA gene on chromosome 11 (74,968,189 to 74,968,292, reverse strand). Ensembl gene ENSG00000200152.
Homologues: Orthologues: chimpanzee U6 (99% identical), macaque U6 (92% identical), mouse Gm25039 (80% identical), guinea pig U6 (62% identical). Paralogues in human: RNU6-1094P (88% identical), RNU6-10P (88% identical), RNU6-11P (88% identical), RNU6-30P (88% identical), RNU6-37P (88% identical), RNU6-742P (88% identical), RNU6-797P (88% identical), RNU6-1 (87% identical), RNU6-1042P (87% identical), RNU6-1145P (87% identical), RNU6-1209P (87% identical), RNU6-1331P (87% identical), and 1288 more.